SOCS2 (suppressor of cytokine signaling 2)
Description:
Substrate-recognition component of a cullin-5-RING E3 ubiquitin-protein ligase complex (ECS complex, also named CRL5 complex), which mediates the ubiquitination and subsequent proteasomal degradation of target proteins, such as EPOR and GHR. Specifically recognizes and binds phosphorylated proteins via its SH2 domain, promoting their ubiquitination. The ECS(SOCS2) complex acts as a key regulator of growth hormone receptor (GHR) levels by mediating ubiquitination and degradation of GHR, following GHR phosphorylation by JAK2. The ECS(SOCS2) also catalyzes ubiquitination and degradation of JAK2-phosphorylated EPOR.
Synonyms: SOCS-2; SSI-2; CIS2; SSI2; STATI2; Cish2
Tractability: Small molecule: a structure with a bound ligand is known. PROTAC: UniProt records ubiquitination sites on it; ubiquitination databases record sites on it.
Gene: Protein-coding gene on chromosome 12 (93,569,808 to 93,583,487, forward strand). Ensembl gene ENSG00000120833.
Subcellular location: Cytoplasm
Subcellular location (Human Protein Atlas): Endoplasmic reticulum
Pathways (Reactome):
Immune System: Growth hormone receptor signaling; Interleukin-7 signaling; Negative regulation of FLT3
Metabolism of proteins: Neddylation
Gene Ontology:
Molecular function: insulin-like growth factor receptor binding; phosphorylation-dependent protein binding; protein binding; ubiquitin-like ligase-substrate adaptor activity; cytokine receptor binding; growth hormone receptor binding; JAK pathway signal transduction adaptor activity
Biological process: cellular response to hormone stimulus; growth hormone receptor signaling pathway; negative regulation of growth hormone receptor signaling pathway; negative regulation of signal transduction; proteasome-mediated ubiquitin-dependent protein catabolic process; response to estradiol; cell surface receptor signaling pathway via JAK-STAT; cytokine-mediated signaling pathway; negative regulation of apoptotic process; negative regulation of receptor signaling pathway via JAK-STAT; regulation of cell growth; regulation of signal transduction; intracellular signal transduction; protein ubiquitination
Cellular component: Cul5-RING ubiquitin ligase complex; cytoplasm; cytosol
Genetic constraint (gnomAD): Loss-of-function variants: 10 observed, 18.69 expected, observed/expected ratio (o/e) 0.53, 90% interval 0.33 to 0.91. The upper end of that interval is the gene's LOEUF score, 0.91, which puts it in group 3 of 6, group 1 being the genes least tolerant of losing a copy. Missense variants: 230 observed, 237.51 expected, observed/expected ratio (o/e) 0.97, 90% interval 0.87 to 1.08. Synonymous variants: 103 observed, 99.03 expected, observed/expected ratio (o/e) 1.04, 90% interval 0.89 to 1.23.
Homologues: Orthologues: chimpanzee SOCS2 (99% identical), macaque SOCS2 (98% identical), guinea pig SOCS2 (96% identical), pig SOCS2 (96% identical), dog SOCS2 (94% identical), rabbit SOCS2 (94% identical), mouse Socs2 (94% identical), rat Socs2 (93% identical), tropical clawed frog socs2 (64% identical), zebrafish socs2 (55% identical), Drosophila melanogaster Socs36E (27% identical), Drosophila melanogaster Socs44A (23% identical). Paralogues in human: CISH (42% identical), SOCS6 (32% identical), SOCS3 (31% identical), SOCS7 (30% identical), SOCS5 (28% identical), SOCS1 (28% identical), SOCS4 (27% identical).
Diseases named in the same sentence as SOCS2 in open-access papers:
SOCS2 is named in the same sentence as 144 diseases in open-access papers, as found by Europe PMC text mining. Sharing a sentence is not in itself a finding about the gene and the disease. The quoted sentences say what the papers report.
hepatocellular carcinoma (62 papers, 2014 to 2025). A malignant tumor that arises from hepatocytes. "In cancer, low SOCS2 gene expression was associated with breast cancer, lung cancer, hepatocellular carcinoma, and ovarian cancer." (PMID 33414813, 2020). "Reduced SOCS2 protein expression is associated with a poorer outcome in diverse human cancers, such as colorectal cancer, breast carcinoma, and hepatocellular carcinoma, suggesting SOCS2 may have some utility as a prognostic biomarker." (PMID 36398696, 2022). "The overexpression of METTL3 in hepatocellular carcinoma (HCC) leads to the degradation of the oncogene SOCS2 through m6A modification, which is associated with poor patient prognosis." (PMID 38649363, 2024). "Previous studies indicated that a decreased expression of SOCS2 was associated with the progression and poor prognosis of hepatocellular carcinoma (HCC)." (PMID 36539807, 2022). "METTL3 is frequently upregulated in hepatocellular carcinoma patients, and the upregulated METTL3 inhibits the expression of tumor suppressor SOCS2 through m6A methylation and promotes the development of hepatocellular carcinoma." (PMID 39006762, 2024). "A previous literature documented that SOCS2 can enhance SLC7A11 ubiquitination to mediate ferroptosis of hepatocellular carcinoma cells." (PMID 38267746, 2024). "For instance, METTL3 is associated with poor prognosis in hepatocellular carcinoma (HCC) patients and promotes HCC cell proliferation through YTHDF2-mediated silencing of SOCS2 transcription." (PMID 38970366, 2024). "It has been reported that high METTL3 expression in primary hepatocellular carcinoma (HCC) increases the levels of m6A modification on the tumor suppressor SOCS2." (PMID 36525280, 2023). "We have selected several genes (SPP1, FLT3, KIF18A, SOCS2) of unclear significance in hepatocellular carcinoma." (PMID 37346073, 2023). "METTL3 promotes hepatocellular carcinoma proliferation and metastasis by promoting m6A modification at the SOCS2 mRNA 3′ end, resulting in accelerated SOCS2 mRNA degradation." (PMID 38102645, 2023). "METTL3 represses the tumor suppressor SOCS2 expression in hepatocellular carcinoma through m6A regulatory mechanisms." (PMID 37529797, 2022). "For instance, in hepatocellular carcinoma, METTL3 is associated with a poor prognosis and inhibits the suppressor of cytokine signaling 2 (i.e., SOCS2) expression through the miR-145/m 6 A/YTHDF2-dependent axis." (PMID 35571068, 2022). "For example, upregulated METTL3 expression was shown to promote gastric cancer and hepatocellular carcinoma progression by promoting, respectively, epithelial to mesenchymal transition and posttranscriptional silencing of SOCS2." (PMID 34507301, 2021). "For example, a document exhibited that SOCS2 expression was decreased in hepatocellular carcinoma, and overexpression of SOCS2 repressed the metastatic potential of hepatocellular carcinoma cells in vivo and in vitro." (PMID 33397365, 2021). "Overexpression of METTL3 significantly promoted tumorigenesis and metastasis of hepatocellular carcinoma, mostly through regulation of SOCS2 expression by an m6qa- and YTHDF2-dependent mechanisms." (PMID 33692753, 2021). "Studies have shown that YTHDF2 induced the targeted degradation of the tumor suppressor SOCS2, thereby promoting the tumor progression of hepatocellular carcinoma, and this regulation depended on the m6A modification induced by METL3." (PMID 33505426, 2020). "More importantly, suppressor of cytokine signaling 2 (SOCS2) was identified as a target of METTL3-mediated m6A modification in hepatocellular carcinoma." (PMID 32709063, 2020). "For instance, METTL3 drives tumorigenicity and metastasis through suppressing suppressor of cytokine signaling 2 (SOCS2) expression in hepatocellular carcinoma." (PMID 32244981, 2020).
hepatocellular carcinoma (continued). "Older Gnmt−/− mice develop hepatocellular carcinoma associated with hypermethylation of RASSF1 (Ras association domain family member 1) and SOCS2 (suppressor of cytokine signaling 2) promoters, and silencing of the respective genes." (PMID 31208147, 2019). "Similarly, in hepatocellular carcinoma, increased m6 A modification of SOCS2 speeds up its degradation, thereby promoting tumor progression." (PMID 40382536, 2025). "In this study, we speculated that SOCS2 may play multiple roles in the progression of hepatic carcinoma and may act as a suppressor gene." (PMID 39307915, 2024). "For instance, the suppressor of cytokine signaling 2 (SOCS2) was identified as a biomarker that predicted the sensitivity of hepatocellular carcinoma (HCC) to radiation therapy by enhancing the ubiquitin-mediated degradation of xCT and facilitating ferroptosis." (PMID 39557844, 2024). "Taken together, ferroptosis contributed to radiosensitization of hepatoma cells, and the acquired radioresistance owing to SOCS2-suppressed could be reversed by RSL3-induced ferroptosis." (PMID 35995846, 2023). "Another study in hepatocellular carcinoma (HCC) cells found that METTL3 promoted proliferation by inhibiting the expression of SOCS2, a transcription factor that can negatively regulate cell proliferation, through m6A-dependent/YTHDF2-mediated mRNA degradation." (PMID 35350378, 2022). "By reviewing the literature, LC16A1-AS1 has been reported to enhance radiosensitivity and repress cell proliferation and invasion by regulating the miR-301b-3p/CHD5 axis in hepatocellular carcinoma and to suppress cell proliferation in cervical squamous cell carcinoma by the miR194/SOCS2 axis." (PMID 35372039, 2022). "SOCS2 also inhibits metastasis in hepatocellular carcinoma, a male-predominant disease." (PMID 33761883, 2021). "Moreover, in hepatocellular carcinoma, the excessive m6A modification of the SOCS2 tumour suppressor gene reduces mRNA stability and accelerates its degradation, which causes tumour progression." (PMID 30031372, 2018). "YTHDF2 has also been shown to induce METTL3‐mediated suppressor of cytokine signaling 2 (SOCS2) mRNA degradation in hepatocellular carcinoma (HCC), therefore driving HCC cell proliferation, migration, and colony formation." (PMID 38721006, 2024). "Collectively, these results indicated that miR-500a-3p promotes CSC-like phenotypes of HCC cell via targeting SOCS2, SOCS4 and PTPN11, which further promotes the progression of hepatocellular carcinoma." (PMID 28750679, 2017). "In hepatocellular carcinoma (HCC), METTL3 suppresses SOCS2 expression in a YTHDF2-dependent manner, while WTAP reduces ETS1 mRNA levels through the m6A mechanism, collectively promoting cell cycle progression and tumor proliferation." (PMID 41446042, 2025). "In hepatocellular carcinoma (HCC), METTL3 has been reported to promote tumor cell proliferation through the YTHDF2-dependent silencing of SOCS2, resulting in the overactivation of the JAK/STAT pathway." (PMID 40136363, 2025). "Additionally, SOCS2 can promote the K48-linked ubiquitination and degradation of SLC7A11 to facilitate ferroptosis of hepatocellular carcinoma (HCC) cells, thus affecting the radiosensitivity and prognosis of this cancer." (PMID 38267746, 2024). "In hepatocellular carcinoma (HCC), for instance, SOCS2 increases radiotherapy sensitivity by enhancing SLC7A11 ubiquitination and ferroptosis." (PMID 37795447, 2023). "A previous study found that the overexpression of METTL3 in hepatocellular carcinoma (HCC) may promote the degradation of the SOCS2 gene, resulting in an abnormal JAK/STAT signaling pathway, causing the proliferation and migration of HCC cells." (PMID 36230944, 2022). "In human hepatocellular carcinoma, METTL3 is frequently up-regulated and can regulate the expression of SOCS2 through an m6A-YTHDF2-dependent mechanism." (PMID 35794583, 2022).
hepatocellular carcinoma (continued). "In hepatocellular carcinoma (HCC), METTL3 enhances the degradation of m6A-containing SOCS2 mRNA together with YTHDF2." (PMID 32303268, 2020). "In human hepatocellular carcinoma, knockdown of METTL3 decreased SOCS2 mRNA modification and increased SOCS2 mRNA expression, suppressing the progression of liver cancer." (PMID 33072746, 2020). "Reduced SOCS2 level is markedly related to advanced TNM stage and appears to be a prognostic marker in hepatocellular carcinoma." (PMID 32536038, 2020). "In summary, this study reports that oncogenic miR-500a-3p promotes the CSCs properties and tumourigenicity by negatively regulating SOCS2, SOCS4 and PTPN11, leading to activation of the STAT3 signalling pathway in hepatocellular carcinoma." (PMID 28750679, 2017). "MiR-589-5p promotes the spheroid formation of CD133+ hepatocellular carcinoma (HCC) cells and their tumorigenicity in vivo by targeting the IL-6 pathway inhibitors SOCS2/5 and PTPNI/11, while it further accelerates tumor chemoresistance via regulation of Stat3 signaling." (PMID 32932969, 2020). "The ectopic expression of SOCS2 and CISH in liver-related cell line leghorn strain M chicken hepatoma (LMH) cell and immortalized chicken preadipocytes (ICP) revealed that these two genes can regulate fatty acid metabolism, adipocyte differentiation, and lipid droplet accumulation." (PMID 33519913, 2020). "In human hepatocellular carcinoma (HCC), highly expressed METTL3 restrains expression of SOCS2 via YTHDF2-mediated degradation." (PMID 31801551, 2019). "In conclusion, we identified a three-gene predictive signature comprised of UPB1, SOCS2 and RTN3 for hepatocellular carcinoma and validated these three genes expression pattern in HCC tissues." (PMID 28717245, 2017). "In hepatocellular carcinoma (HCC), METTL14 was identified to be involved in the malignant progression of HCC by regulating m6A downstream targets, including cysteine sulfinic acid decarboxylase (CSAD), glutamic- oxaloacetic transaminase 2 (GOT2), and suppressor of cytokine signaling 2 (SOCS2)." (PMID 35731272, 2023). "Five genes (PSRC1, SOCS2, TMEM45A, CCT5, and STC2) were selected from the TCGA training dataset to construct the prognostic CSGscore signature, which could precisely predict the prognosis of hepatocellular carcinoma patients both in the training and validation datasets." (PMID 36589233, 2022). "In hepatocellular carcinoma (HCC), METTL3-mediated increase in the m6A level of SOCS2 mRNA promotes degradation of this ubiquitous cytokine signaling transducer through an m6A YTHDF2-dependent mechanism; the decreased expression of SOCS2 promotes HCC progression." (PMID 34105069, 2021).
liver cancer (40 papers, 2019 to 2025). An epithelial or non-epithelial malignant neoplasm that arises from the liver. "It was also proven that YTHDF2 causes m6A-mediated SOCS2 mRNA degradation and contributes to liver cancer progression." (PMID 33726814, 2021). "The study also indicated that SOCS2 and SOCS4 are risk‐related genes for predicting the prognosis of patients with liver cancer." (PMID 39307915, 2024). "Given the reduced expression of P15 and SOCS2 in drug-resistant liver cancer cell lines, we opted to knock down these genes in parental cells and overexpress them in drug-resistant cell lines." (PMID 38528605, 2024). "To investigate the impact on sorafenib resistance, we manipulated the expression of tumor suppressor genes (P15 or SOCS2) in liver cancer cell lines." (PMID 38528605, 2024). "METTL3 is overexpressed in colorectal, gastric, and liver cancers, promoting cancer cell proliferation by inhibiting the tumor suppressor SOCS2." (PMID 39473440, 2024). "Next, we assessed the prognostic value of SOCS family members in HCC, and the results indicated that SOCS2 and SOCS4 are risk‐related genes in patients with liver cancer." (PMID 39307915, 2024). "Such as, METTL3 promotes liver cancer progression by regulating SOCS2 in an YTHDF2-dependent manner." (PMID 36008805, 2022). "Research shows that METTL3 promotes cancer progression through YTHDF2 dependent posttranscriptional silencing of SOCS2 in liver cancer." (PMID 35595748, 2022). "For instance, METTL3 promotes liver cancer progression via regulating SOCS2 expression in an m6A-dependent manner." (PMID 36008805, 2022). "METTL3 is also a tumor suppressor—it promotes the occurrence and development of liver cancer by reducing the stability of SOCS2 mRNA through m6A-YTHDF2-dependent pathways." (PMID 33540684, 2021). "It has been shown that YTHDF2 targets a plethora of mRNAs for degradation in cancers, such as, TNFR2, c-Myc and CEBPA in leukemia, EGFR, IL11, SERPINE2 and SOCS2 in liver cancer, and PD-1, CXCR4, and SOX10 in melanoma." (PMID 33658012, 2021). "It binds SOCS2 mRNA and mediates its degradation to promote liver cancer progression, while METTL3 regulates the m6A level of SOCS2 mRNA106." (PMID 33795663, 2021). "Recent research showed that METTL3 is involved in liver cancer development by regulating the proliferation and differentiation of liver cells via inducing SOCS2 mRNA m6A modification." (PMID 34616359, 2021). "Previously, another group has shown that the m6A modification was involved in promoting liver cancer progression through YTHDF2‐mediated SOCS2 degradation." (PMID 32368828, 2020). "METTL3 mediates YTHDF2-dependent post-transcriptional silencing of SOCS2(Suppressor of Cytokine Signaling 2) to promote liver cancer progression." (PMID 32765970, 2020). "PPARGC1A and SOCS2 are considered to be tumor suppressors in liver cancer, while SLC25A members are involved in mitochondrial Ca2+ signaling important for hepatocyte physiology." (PMID 30867900, 2019). "Additionally, m6A-dependent negative regulations of TGF-β, Ras signaling pathways, and the tumor suppressor genes HINT2 and SOCS2 have also been observed in ocular melanoma, liver cancer, and other related malignancies." (PMID 40136363, 2025). "Our clinical data suggest that SOCS2, a key negative regulator of JAK/STAT signaling, may be associated with the risk of liver cancer progression." (PMID 39307915, 2024). "Moreover, the methyltransferase METTL3 was discovered to regulate the degradation of SOCS2 mRNA, enhancing the progression of liver cancer in a YTHDF2-mediated m6A-dependent manner." (PMID 34996459, 2022).